JPH1 (junctophilin 1)
Description:
Junctophilins contribute to the formation of junctional membrane complexes (JMCs) which link the plasma membrane with the endoplasmic or sarcoplasmic reticulum in excitable cells. Provides a structural foundation for functional cross-talk between the cell surface and intracellular calcium release channels. JPH1 contributes to the construction of the skeletal muscle triad by linking the t-tubule (transverse-tubule) and SR (sarcoplasmic reticulum) membranes.
Synonyms: JP-1; JP1; CMT2K; CMYO25
Tractability: Antibody: UniProt places it where antibodies can reach, with medium confidence; UniProt predicts a signal peptide or a membrane-spanning region; its Gene Ontology location is reachable by antibodies, with medium confidence. PROTAC: ubiquitination databases record sites on it.
Gene: Protein-coding gene on chromosome 8 (74,234,700 to 74,321,592, reverse strand). Ensembl gene ENSG00000104369.
Subcellular location: Cell membrane; Endoplasmic reticulum membrane; Sarcoplasmic reticulum membrane
Subcellular location (Human Protein Atlas): Nucleoplasm
Gene Ontology:
Molecular function: protein binding; structural constituent of muscle
Biological process: calcium ion transport into cytosol; regulation of cardiac muscle contraction by calcium ion signaling; regulation of release of sequestered calcium ion into cytosol by sarcoplasmic reticulum
Cellular component: nucleoplasm; endoplasmic reticulum membrane; junctional membrane complex; junctional sarcoplasmic reticulum membrane; plasma membrane; sarcoplasmic reticulum; endoplasmic reticulum; sarcoplasmic reticulum membrane; Z disc
Genetic constraint (gnomAD): Loss-of-function variants: 11 observed, 49.87 expected, observed/expected ratio (o/e) 0.22, 90% interval 0.14 to 0.37. The upper end of that interval is the gene's LOEUF score, 0.37, which puts it in group 1 of 6, group 1 being the genes least tolerant of losing a copy. Missense variants: 777 observed, 897.98 expected, observed/expected ratio (o/e) 0.87, 90% interval 0.81 to 0.92. Synonymous variants: 359 observed, 361.19 expected, observed/expected ratio (o/e) 0.99, 90% interval 0.91 to 1.09.
Homologues: Orthologues: chimpanzee JPH1 (99% identical), macaque JPH1 (99% identical), dog JPH1 (96% identical), rabbit JPH1 (95% identical), pig JPH1 (94% identical), rat Jph1 (93% identical), mouse Jph1 (93% identical), guinea pig JPH1 (86% identical), tropical clawed frog jph1 (76% identical), zebrafish jph1b (71% identical), zebrafish jph1a (66% identical), Caenorhabditis elegans jph-1 (39% identical), and 1 more. Paralogues in human: JPH3 (53% identical), JPH2 (53% identical), JPH4 (39% identical).
Diseases named in the same sentence as JPH1 in open-access papers:
JPH1 is named in the same sentence as 34 diseases in open-access papers, as found by Europe PMC text mining. Sharing a sentence is not in itself a finding about the gene and the disease. The quoted sentences say what the papers report.
breast carcinoma (3 papers, 2016 to 2021). "In conclusion, the expression of PTP4A3 and JPH1 correlates with risk of liver metastasis in colorectal cancer and breast cancer." (PMID 31748560, 2019). "We measured the expression of PTP4A3 and JPH1 in a breast cancer cohort by qPCR and used it to calculate the risk score in a series of 463 tumors for which the time and site of relapse were known (271 hormone receptor-positive, 86 triple-negative and 106 HER2-positive)." (PMID 31748560, 2019). "Meanwhile, although piR-34736 was found to be underexpressed in breast cancers and lnc-JPH1-7 was also identified in esophageal (ESCCAL-1) and lung (LCAL80) squamous cell carcinomas, their clinical and molecular significance has, up to now, remained uninvestigated." (PMID 27323410, 2016).
neuroblastoma (2 papers, 2012 to 2020). Neuroblastoma (NB) is the most common solid, extracranial childhood tumor. "One study reported that JPH1 was upregulated in the poor outcome group in neuroblastoma patients." (PMID 22912720, 2012).
uveal melanoma (2 papers, 2019 to 2021). A melanoma derived from melanocytes of the uveal tract. "We derived and validated a prognostic score that predicted relapse in uveal melanoma based on the weighted expression of only two genes (PTP4A3 and JPH1) and applied it to the prediction of liver relapse in other malignancies." (PMID 31748560, 2019).
adult T-cell leukemia (1 paper, 2021). "A mutation in the JPH1 gene was noted in a patient with human T-lymphotropic virus type-1 (HTLV-1)-associated myelopathy/tropical spastic paraparesis who subsequently developed adult T-cell leukemia." (PMID 36046118, 2021).
Charcot-Marie-Tooth disease (1 paper, 2022). An inherited degenerative disorder involving the peripheral nerves. "Inherited JPH1 variants act as a disease-modifier in Charcot-Marie-Tooth disease caused by variants in ganglioside-induced differentiation-associated protein 1 (GDAP1)." (PMID 35001666, 2022). "JPH1 has been revealed as a modifier gene of a hereditary motor and sensory neuropathy known as Charcot-Marie-Tooth disease." (PMID 35001666, 2022).
colon adenocarcinoma (1 paper, 2021). "In the literature, the association of CACNA1D with improved survival outcomes in colon adenocarcinoma, and of JPH1 with improved survival outcomes in small-cell lung carcinoma, was particularly strong." (PMID 36046118, 2021).
congenital myopathy (1 paper, 2024). "Our findings suggest that loss of JPH1 results in a congenital myopathy with prominent facial, bulbar and ocular involvement." (PMID 39209426, 2024). "Our results, show for the first time that bi-allelic null variants in JPH1 cause a congenital myopathy characterised by prominent facial and ocular muscle weakness." (PMID 39209426, 2024). "Our results demonstrate that loss-of-function variants in JPH1, coding for junctophillin-1, result in a congenital myopathy, characterised by global distribution of muscle weakness and wasting, but with prominent facial muscle weakness, bilateral ptosis, exercise intolerance and fatigability." (PMID 39209426, 2024). "Our deep phenotyping and novel genetic findings expand the spectrum of congenital myopathies caused by defects in triad proteins and provide evidence for the first time that loss of JPH1 results in a skeletal muscle disease and should be classified as a triadopathy." (PMID 39209426, 2024).
dilated cardiomyopathies (1 paper, 2018). "Moreover, mutations in the human JPH2 gene are associated with hypertrophic and dilated cardiomyopathies; mutations in JPH3 are responsible for the neurodegenerative Huntington's disease-like-2 (HDL2), whereas JPH1 acts as a genetic modifier in Charcot–Marie–Tooth 2K peripheral neuropathy." (PMID 29208631, 2018).
endometrial carcinoma (1 paper, 2021). A malignant tumor arising from the epithelium that lines the cavity of the uterine body. "JPH1 was among the top 20 genes associated with survival in endometrial carcinoma; whether JPH1 was associated positively or negatively with survival was not reported." (PMID 36046118, 2021).
gastric cancer (1 paper, 2021). A primary or metastatic malignant neoplasm involving the stomach. "JPH2 was among 10 individual genes of a DNA-methylation signature associated with overall survival of gastric cancer patients: in contrast to the JPH1 observations of the present study, higher JPH2-methylation (gene-downregulation) was associated with longer survival." (PMID 36046118, 2021).
hypertrophic cardiomyopathies (1 paper, 2011). "Among the four junctophilin-like proteins in mammals (JPH1-4), JPH1 is expressed mainly in skeletal muscle while JPH2 is also expressed in cardiac muscle and implicated in hypertrophic cardiomyopathies." (PMID 21797990, 2011).
lung adenocarcinoma (1 paper, 2026). A carcinoma that arises from the lung and is characterized by the presence of malignant glandular epithelial cells. "Applied to lung adenocarcinoma (LUAD) scRNA-seq data, PICDGI recovered known oncogenes and tumor suppressors and nominated novel candidate drivers, including JPH1 and CHEK1, which are implicated in calcium signaling, mitochondrial regulation, and DNA repair." (PMID 42044093, 2026).
lung carcinoma (1 paper, 2021). "JPH1 was among the upregulated genes in an analysis of lung cancer." (PMID 36046118, 2021).
melanoma (1 paper, 2021). A malignant, usually aggressive tumor composed of atypical, neoplastic melanocytes. "By contrast, in uveal-melanoma tissue, JPH1 expression was downregulated compared to normal tissue." (PMID 36046118, 2021).
muscular dystrophy (1 paper, 2022). Muscular dystrophy (MD) refers to a group of more than 30 genetic diseases characterized by progressive weakness and degeneration of the skeletal muscles that control movement. "It is presently unknown whether other mechanisms such as altered transcriptional control, RNA processing, or translational control contribute to the loss of JPH1 in muscular dystrophies." (PMID 35001666, 2022). "Interestingly, aberrant JPH1 proteolysis was seen in the mdx mouse model of muscular dystrophy, providing an association with the pathogenesis of a primary muscle disease." (PMID 35001666, 2022).
Skeletal myopathy (1 paper, 2022). "Loss of JPH1 protein levels can cause skeletal myopathy, while loss of cardiac JPH2 levels causes heart failure and atrial fibrillation, among other disease." (PMID 35001666, 2022). "For example, loss of JPH1 expression levels has been linked to skeletal myopathies and dystrophies." (PMID 35001666, 2022).
squamous cell lung carcinoma (1 paper, 2021). A carcinoma arising from squamous bronchial epithelial cells. "Consistent with our findings, JPH1 was one of 14 of 7,222 genes identified as being strongly associated with a better prognosis in squamous-cell lung carcinoma." (PMID 36046118, 2021).
tumor (3 papers, 2016 to 2026). "The authors also highlighted a significant correlation between Lnc-JPH1-7 and the advanced, tumor stage." (PMID 36046118, 2021). "If in the present study, JPH1 is upregulated in OAC and associated with improved survival, it would suggest that miR-145 is interacting with JPH1 post-transcriptionally to favor tumor suppression." (PMID 36046118, 2021). "CACNA1D, JPH1, and ATP2C2 were also upregulated in advanced OAC tumor grades and nodal-metastatic stages in both datasets." (PMID 36046118, 2021). "Further analysis revealed that JPH1 was upregulated across advanced OAC-tumor grades and OAC nodal-metastatic stages." (PMID 36046118, 2021). "Furthermore, there were significant differences in the transcription levels of CACNA1D, JPH1, and ATP2C2 between various tumor grades and nodal-metastatic stages in both datasets." (PMID 36046118, 2021).
cancer (2 papers, 2012 to 2019). A tumor composed of atypical neoplastic, often pleomorphic cells that invade other tissues. "It is important to note that some of the genes that we have identified and confirmed by qRT-PCR (such as AKR1B10 and JPH1) may serve as potential candidates for targeted therapeutics in cancer." (PMID 22912720, 2012). "Very little is known about the role of junctophilin-1 (JPH1) in cancer." (PMID 22912720, 2012).
myopathy (1 paper, 2024). A disease of the muscle in which the muscle fibers do not function properly. "Further characterisation of the spectrum of pathologies associated with JPH1-related myopathy will be needed as additional patients are identified." (PMID 39209426, 2024).
neuromuscular disease (1 paper, 2024). "Analysis of RNA-seq data showed that mRNA expression of other key genes of the triad are unaltered in JPH1 patient’s skeletal muscle compared with healthy controls and other neuromuscular disease biopsies." (PMID 39209426, 2024).
peripheral neuropathy (1 paper, 2018). A disorder affecting the peripheral nervous system. "Human JPH1 is a modifier of the GDAP1 mutations causing Charcot–Marie–Tooth peripheral neuropathy." (PMID 29208631, 2018). "Recently, JPH1 has been described as a genetic modifier for the Charcot–Marie–Tooth 2K (CMT2K) peripheral neuropathy." (PMID 29208631, 2018).
JPH1 also shares sentences with these, for which no sentence is quoted: colorectal cancer (2 papers); squamous cell carcinoma (2); cardiovascular diseases (1); cholangiocarcinoma (1); head and neck squamous cell carcinoma (1); Hypertension (1); metabolic disease (1); Myelopathy (1); ptosis (1); small cell lung carcinoma (1); tobacco use disorder (1); tropical spastic paraparesis (1).